CHL1 (cell adhesion molecule L1 like)
Diseases named in the same sentence as CHL1 in open-access papers (continued):
Sharing a sentence is not in itself a finding about the gene and the disease.
tumor (continued). "CHL1, a gene associated in this study with SBP in AA, is a known tumor suppressor gene; CHL1 SNPs have been shown to associate with LDL in interaction models with statin use." (PMID 24400021, 2013). "CHL1 is expressed in normal tissues besides the brain and is expressed in a variety of human cancer cell lines and primary tumor tissues." (PMID 21408220, 2011). "Summary of CHL1 expression in 11 tumor types as measured with the Clontech Cancer Profiling Arrays I and II." (PMID 21408220, 2011). "Thus, the rescue assays proved that miR-338-3p directly targeted CHL1 to inhibit NSCLC cells growth while promoting tumor cells apoptosis." (PMID 34718336, 2021). "Moreover, CHL1 knockdown significantly suppressed tumor cells proliferation and promoted apoptosis and CHL1 overexpression promoted tumor cells proliferation and inhibited apoptosis, demonstrating that CHL1 acts as an oncogene in NSCLC metastasis." (PMID 34718336, 2021). "Emerging evidence shows that CHL1 plays a pivotal role in different tumor types." (PMID 34718336, 2021). "Besides, we confirmed that miR-338-3p directly sponged with CHL1 to mediate tumor cells progression." (PMID 34718336, 2021). "MiR-182 was also shown to promote tumor growth and invasion by inhibiting the CHL1 gene expression." (PMID 35186709, 2021). "Furthermore, exosomal miR-338-3p suppresses tumor cells proliferation and induces apoptosis by inhibiting CHL1 through MAPK signaling inactivation." (PMID 34718336, 2021). "In this study, we investigated whether ERM proteins interact with CHL1 in NB cells, thus inducing a higher differentiation degree and lower tumor aggressiveness." (PMID 33326488, 2020). "Material and Methods: Expression of CHL1 was analyzed in primary tumor specimens and metastases." (PMID 32284790, 2020). "Soluble CHL1 or the remaining intracellular domain might then foster tumor cell migration and invasiveness." (PMID 32284790, 2020). "Another recent study also demonstrated a tumor suppressive function of CHL1 in neuroblastoma." (PMID 32284790, 2020). "Furthermore, we investigated the potential of the shed CHL1 as a peripheral tumor marker in sera of GIST patients." (PMID 32284790, 2020). "The study of the tumor suppressive role of CHL1 was characterized by an in vitro and in vivo assay." (PMID 31523184, 2019). "In conclusion, CHL1 and NrCAM as members of the L1 superfamily may play an important role in early tumor development." (PMID 31989042, 2019). "The tumor-suppressive function of CHL1 was characterized in two NPC cell lines (SUNE1 and C666)." (PMID 31523184, 2019). "CHL1 could co-localize with adhesion molecule Integrin-β1, the expression of CHL1 was positively correlated with Integrin-β1 and another known tumor suppressor gene (TSG) Merlin." (PMID 31523184, 2019). "The results indicated that the ratio of cells in the S phase was significantly decreased in CHL1-transfected cells compared to non-transfected cells (P<0.05, Student's t-test), indicating that CHL1 arrest tumor growth at the G1/S checkpoint in the growth cycle." (PMID 31523184, 2019). "In addition, experimental metastasis assay was used to study the in vivo effect of CHL1 on tumor metastasis." (PMID 31523184, 2019). "In conclusion, CHL1 is a vital tumor suppressor in the carcinogenesis of NPC." (PMID 31523184, 2019). "Moreover, we further investigated the tumor suppressive potential of CHL1 by in vivo tumor formation assay in nude mice." (PMID 31523184, 2019). "Based upon our results, we propose that CHL1 functions as a tumor suppressor gene in NB." (PMID 29899830, 2018). "In our experiments, knockdown of CHL1 promoted the tumor growth." (PMID 30134821, 2018). "Since CHL1 has been reported as a tumor suppressor, we supposed that miR-21-5p may promote tumor development via inhibiting CHL1 expression." (PMID 30134821, 2018). "The expression of miR-21-5p and CHL1 in tumor was accessed by western blot and qRT-PCR." (PMID 30134821, 2018).
tumor (continued). "CHL1 over-expression significantly inhibited tumor growth compared with control mice." (PMID 29899830, 2018). "These combined data indicated that the functional expression of CHL1 is tumor phenotype dependent." (PMID 29089868, 2017). "Our results are consistent with the only study to date to demonstrate the biological role of CHL1 in BC, in which tumour cell proliferation and invasion were suppressed and stimulated by overexpression and depletion of CHL1, respectively, due to its interaction with the cytoskeleton." (PMID 28178655, 2017). "However, the total increased tumor volume in mice treated with siRNA targeting CHL1 was significantly lower than that in mice treated with control siRNA (p < 0.05 vs. control siRNA, data not shown)." (PMID 29089868, 2017). "At low magnification (20x) accumulation within cells in the connective tissue in the stroma was observed, but uptake into individual CHL-1 HER3 expressing tumor cells was clearly distinguished at high magnification (63x) as distinct punctate signal within the cytoplasm." (PMID 28448604, 2017). "Re-expression of CHL1 on the edge of the tumor mass and around tumor vessels could promote migration and local invasive growth and furthermore allow initiating the metastatic process." (PMID 21408220, 2011). "One of us predicted previously that the cytoplasmic end of CHL1 protein might interact with the cytoskeleton and might induce/regulate filopodia formation driving tumor cell migration and invasion." (PMID 21408220, 2011). "Initially, during the primary tumor growth CHL1 could act as a putative tumor suppressor and is silenced to facilitate in situ tumor growth for 11 cancer types." (PMID 21408220, 2011). "The studies published by us and other authors (see Introduction) suggested that the CHL1 gene could be one of the putative tumor suppressor genes localized on human chromosome 3." (PMID 21408220, 2011). "Our results suggested a dual role of the CHL1 in tumorigenesis: it may contribute to initial tumor growth and then to progression and finally tumor spread/metastasis." (PMID 21408220, 2011). "Similarly, CHL1 has been reported as a tumor suppressor gene in multiple cancer-related studies." (PMID 41374320, 2025). "In conclusion, our study divided ccRCC into distinct immune clusters and thereby identified two DEGs, namely, PTPRG and CHL1, which were validated to play a crucial role in inhibiting tumor growth and might be responsible for the formation of distinct immune clusters in ccRCC." (PMID 35433461, 2022). "Thus, the expression of CHL1, NrCAM, L1CAM, and ALCAM may be associated with a less aggressive tumor and, as a consequence, with a better prognosis." (PMID 31989042, 2019). "Thus, the cases with CHL1 up-regulation could serve as examples of CHL1 involvement both in initial and possibly in further progression and invasive tumor growth." (PMID 21408220, 2011). "Moreover in four metastases (4I, 14O, 14V, 24K) of 12 available for analysis cases (i.e. when a primary tumor and metastasis for the same patient were accessible) we detected an increased CHL1 expression in metastasis compared to primary tumor (ovary, colon and breast)." (PMID 21408220, 2011). "The screened candidates, as the targets of miR-21 and miR-21*, included a large number of oncogenic proteins and tumour suppressors, such as Ras, GRHL3, CHL1, PDCD4, PTEN, RECK and HNRPK." (PMID 35421166, 2022). "Conversely, the downregulation of the CHL1 gene inhibited NSCLC cells’ growth and promoted tumor cells’ apoptotic rate." (PMID 34718336, 2021). "Oncogenic miRNA-10a-5p directly regulates multiple tumor-suppressive genes, namely transcription factor AP-2 gamma (TFAP2C), phosphatase and tensin homolog (PTEN) and cell adhesion molecule L1 like (CHL1)." (PMID 32756339, 2020). "The chart showed a significant difference (P<0.01) in the levels of CHL1 between NPC and paired non-tumor tissues." (PMID 31523184, 2019).
tumor (continued). "Conversely, suppression of CHL1 promotes the activation of Rho GTPases, of related MAPK pathways, and of p-Akt inducing cell proliferation and tumor progression." (PMID 29899830, 2018). "The uncharacterized early passage cell lines HS839T, HS600T, HS934T, HS895T, HS940T, and HS688AT as well as CHL1 and HMCB, two commonly derived cell lines with high SNP identity, form a cluster with poor correlation across all tumor samples." (PMID 29383127, 2017). "Of these genes, Pax3, Irx5, and Chl1 were also differentially regulated between the Olig2-compartments of BSG and CG suggesting that they represent biological differences within the tumor cells." (PMID 25330836, 2014). "The cell adhesion molecule Chl1 had not been described in the context of fibrosis so far but is thought to be a tumor suppressor and potential biomarker for survival in lung cancer." (PMID 35842487, 2022). "GRN, CD5L, ENO1, CHL1, CRISP3, VASN, and TNIK promote the invasive ability of tumor cells." (PMID 32953262, 2020). "By up-regulating epithelial markers and down-regulating mesenchymal markers CHL1 could induce mesenchymal-epithelial transition (MET), a key step in preventing tumor invasion and metastasis." (PMID 31523184, 2019). "In this study, we show for the first time that the CHL1 gene, located in this region, is silenced in a subset of invasive BC cases due to promoter hypermethylation, but not in adjacent-to-tumour tissue and non-neoplastic tissue from mammoplasties." (PMID 28178655, 2017). "Consistent with the observed hypermethylation, we have found that tumour cells in BC tissues have a lower level of CHL1 expression compared with non-neoplastic adjacent-to-tumour cells." (PMID 28178655, 2017). "During initial growth CHL1 is not expressed (silenced) in tumor cells to facilitate in situ tumor growth." (PMID 21408220, 2011). "There was no evident correlation between the change of the CHL1 expression and the tumor progression." (PMID 21408220, 2011). "Tumor samples of Inserm series were predicted in 2 and 4 subtypes molecular classification using a predictor based on nine genes: ADAM19, ETS1, and PDCD1LG2 for C1 and C2; CLDN1, DSC3, and SLC24A3 for C1A and C1B; CHL1, ECM2, and PTPN13 for C2A and C2B subtype prediction." (PMID 32083805, 2020). "In brief, over-expression of CHL1 in IMR-32 NB cell line abrogated anchorage-independent colony formation, inhibited proliferation and invasion, impaired migration and growth, induced neuronal differentiation, and dampened tumor growth in orthotopic xenografts mouse model." (PMID 29899830, 2018). "No specific CHL-1 tumor cell labeling was observed with the VivoTag 680 labeled IgG." (PMID 28448604, 2017). "Since DNA methylation is a well-known mechanism of gene expression regulation, the expression pattern of the CHL1 protein was measured by immunohistochemistry in 57 BC tissues, their adjacent-to-tumour counterparts and 20 non-neoplastic tissues from reduction mammoplasties." (PMID 28178655, 2017).
cancer (47 papers, 2009 to 2025). A tumor composed of atypical neoplastic, often pleomorphic cells that invade other tissues. "Alteration of CHL1 has been implicated in the development of different cancers, including colon cancer." (PMID 30134821, 2018). "The deregulated activity of Chl1/ChlR1 has been associated with cancer." (PMID 29875144, 2018). "But mutations in rs425366 may modulate CHL1 gene biological function in different human cancer cell lines." (PMID 29568376, 2018). "The yeast DDX11 homolog, CHL1, is a highly connected SL hub with many genes involved in cancer-relevant processes, but the mammalian GIs of DDX11 are only recently being defined." (PMID 38478595, 2024). "DDX11 plays an important role in DNA replication, repair, and sister chromatid cohesion, and the yeast ortholog, Chl1, is a highly connected SL hub that interacts with many genes involved in cancer-relevant processes." (PMID 38478595, 2024). "An increasing number of studies demonstrated a role of CHL1 in cancer growth, invasion and migration for different entities." (PMID 32284790, 2020). "In review of previous researches, biological role and mechanism of CHL1 gene are issues in different human cancers." (PMID 29568376, 2018). "Other data testified that abnormal expression of CHL1 gene inhibited cancer cells clonogenicity and migration in nasopharyngeal carcinoma." (PMID 29568376, 2018). "A previous reported the low expression of CHL1 in majority of primary cancers and its expression is increased in the metastatic or invasive tumor." (PMID 28243201, 2017). "A total of three differentially hypermethylated genes (CCNE1, PON3, and CCNDBP1) and two differentially hypomethylated genes (DDX43 and CHL1) were selected for the validation based on their β-value and association with CRC as well as other cancers." (PMID 28243201, 2017). "In one study, frequent down-regulation of CHL1 was detected in 11 types of cancer, mainly including breast, kidney, colon, thyroid, and stomach." (PMID 29089868, 2017). "Downregulation of CHL1 has been implicated in several cancers including 48% of all CRC cases, and hypermethylation of CHL1 is associated with increased rates of deletions and MSIs in Iranian CRC specimens." (PMID 27111221, 2016). "We used Cancer Profiling Arrays I and II (Clontech) to test the CHL1 expression in a large sample of human primary tumors including breast, lung, kidney, ovary, colon, stomach and others." (PMID 21408220, 2011). "We used Clontech Cancer Profiling Arrays (19 different types of cancers, 395 samples) to analyze expression of the CHL1 gene." (PMID 21408220, 2011). "CHL1 behavior in cancer is thus strikingly similar to L1 and LOX which both work through the actin network." (PMID 21408220, 2011). "According to Oncomine preliminary data based on microarray analysis, the CHL1 expression also varies in several major cancer types – renal, cervical, colon, ovary, lung, stomach and breast cancer." (PMID 21408220, 2011). "The CHL1 up-regulation (frequency from 20% to 100%) was found in lung, ovary, uterus, liver, skin, prostate, stomach, cervix and trachea cancers." (PMID 21408220, 2011). "It was found that CHL1 is a significant factor during the malignant progression of cancer." (PMID 33240104, 2020). "In other entities, effects of CHL1 on biological functions of cancer cells have also been reported." (PMID 32284790, 2020). "Both in vitro and in vivo assays supported the hypothesis and these findings strongly suggest that the function of CHL1 could inhibit both cancer progression and metastasis." (PMID 31523184, 2019). "Close Homologue of L1 (CHL1) gene plays a crucial role in the progress of cancer." (PMID 29568376, 2018). "Neural cell adhesion molecule L1 (CHL1) is a neural adhesion molecule, which may function in signal transduction pathways and also participate in normal tissues and various of human cancers." (PMID 30134821, 2018).
cancer (continued). "CHL1 therefore could belong to the new rapidly growing category of cancer genes that may function either as TSGs or oncogenes." (PMID 21408220, 2011). "Our results suggested that CHL1 is involved in the development of different human cancers." (PMID 21408220, 2011). "Finally CHL1 gene promoted cancer cells growth, migration and invasion." (PMID 29568376, 2018). "Our results indicated that the CHL1 gene could be important for the development of major human cancers, and also allowed to suggest a hypothesis on a probable dual role of CHL1, although only for three types of cancer (ovary, colon and breast) supportive data were thus far obtained." (PMID 21408220, 2011). "This study suggested that CHL1 might contribute to cancer invasive growth and metastasis." (PMID 21408220, 2011). "As a CAM member, CHL1 and L1CAM another CAM have been reported in cancer development and metastasis in ovarian 17, breast 18, colon 19, pancreatic 20 and gallbladder 21 cancers." (PMID 31523184, 2019). "Of the genes differentially expressed between two group cancers, HTR2B, CHL1, the ZNF family, YWHAZ and FYN were the most significantly altered." (PMID 24597767, 2014). "Noteworthy, several candidate susceptibility genes (PRKCA, BMP6, ADAMTS19, ARHGAP6, FUT9/8, FAM108C1, CHL1, BTBD9 and WDR52) are involved in the actin cytoskeleton arrangement, cell adhesion and cell motility processes, which are important for cancer invasion and metastasis." (PMID 22532847, 2012). "CHL1 is a member of the L1 gene family of neural cell adhesion molecules, which may also play negative role in the growth of certain cancers." (PMID 35127542, 2022).
infection (4 papers, 2007 to 2020). The state of being infected such as from the introduction of a foreign agent such as serum, vaccine, antigenic substance or organism. "We identified 11 genes that were significantly altered after infection with both viruses, and among these genes, 6 were up-regulated after infection (Chl1, Nlrp12, Plk1, Cyfip2, Adamts3, and Pdzk1)." (PMID 30713529, 2018).
neurological disorders (4 papers, 2012 to 2025). "Additionally, genes previously associated with neurological disorders were similarly up regulated, such as Mdga2, Clu, Epha3, Chl1, Cntn4, Cdh23, and Pard3b." (PMID 30628890, 2019).
neurodevelopmental disorder (3 papers, 2020 to 2025). A behavioral and cognitive disorder with onset during the developmental period that involves impaired or aberrant development of intellectual, motor, or social functions. "Among the DEGs, strong evidence of involvement in neurodevelopmental disorders was reported for 15 of them (“definitive” gene list from SysNDD, e.g., PLP1, RGS6, and SCN3A) and moderate evidence for 10 more (“limited” gene list from SysNDD, e.g., UNC13A, NMNAT2, and CHL1)." (PMID 40182141, 2025).
CHL1 also shares sentences with these, for which no sentence is quoted: neuroendocrine tumors (6 papers); small cell lung carcinoma (5); neurodegenerative disease (4); adenocarcinoma (3); amyotrophic lateral sclerosis (3); astrocytomas (3); leukemia (3); Obesity (3); acute lymphoblastic leukemia (2); acute myeloid leukemia (2); GNE myopathy (2); Hydrocephalus (2); lymphoma (2); metabolic syndrome (2); multiple myeloma (2); pancreatic cancer (2); sarcoma (2); Stroke (2); type 2 diabetes (2); Wilms tumor (2); adrenocortical tumors (1); amelanotic melanoma (1); ameloblastoma (1); aplastic anemia (1); asthma (1); Ataxia (1); atopic dermatitis (1); brain disorder (1); carcinoid tumor (1); cardiac hypertrophy (1).
A further 59 diseases each share a sentence with CHL1 in 1 paper.